MGAT4D (MGAT4 family member D)
Description:
May play a role in male spermatogenesis. In vitro acts as inhibitor of MGAT1 activity causing cell surface proteins to carry mainly high mannose N-glycans. The function is mediated by its lumenal domain and occurs specifically in the Golgi. A catalytic glucosyltransferase activity is not detected. May be involved in regulation of Sertoli-germ cell interactions during specific stages of spermatogenesis.
Synonyms: GnT1IP
Tractability: Antibody: UniProt predicts a signal peptide or a membrane-spanning region.
Gene: Protein-coding gene on chromosome 4 (140,442,262 to 140,498,377, reverse strand). Ensembl gene ENSG00000205301.
Subcellular location: Golgi apparatus membrane; Endoplasmic reticulum membrane
Gene Ontology:
Molecular function: acetylglucosaminyltransferase activity
Biological process: protein N-linked glycosylation; negative regulation of glycoprotein biosynthetic process
Cellular component: endoplasmic reticulum; endoplasmic reticulum-Golgi intermediate compartment; Golgi membrane; Golgi stack; endoplasmic reticulum membrane; membrane
Homologues: Orthologues: chimpanzee MGAT4D (97% identical), macaque MGAT4D (95% identical), pig MGAT4D (75% identical), dog MGAT4D (74% identical), rabbit MGAT4D (70% identical), mouse Mgat4d (63% identical), rat Mgat4d (61% identical), tropical clawed frog mgat4d (37% identical), Drosophila melanogaster Mgat4a (28% identical), Drosophila melanogaster Mgat4b (24% identical), zebrafish zgc:101663 (22% identical). Paralogues in human: MGAT4A (38% identical), MGAT4B (37% identical), MGAT4C (23% identical).
Diseases named in the same sentence as MGAT4D in open-access papers:
MGAT4D is named in the same sentence as 2 diseases in open-access papers, as found by Europe PMC text mining. Sharing a sentence is not in itself a finding about the gene and the disease. The quoted sentences say what the papers report.
Sertoli Cell-Only Syndrome (1 paper, 2020). A type of male infertility in which no germ cells are visible in any of the biopsied SEMINIFEROUS TUBULES (type I) or in which germ cells are present in a minority of tubules (type II). "For example, men with Sertoli Cell Only syndrome have very low levels of MGAT4D expression." (PMID 32034218, 2020).
MGAT4D also shares sentences with these, for which no sentence is quoted: Infertility (1 paper).